EGFR (epidermal growth factor receptor)
Diseases named in the same sentence as EGFR in open-access papers (continued):
Sharing a sentence is not in itself a finding about the gene and the disease.
glioblastoma (continued). "However, one SETD2-mutant astrocytoma in an older patient (#6) also harbors an EGFR mutation and lacks IDH changes, and so is in essence a “molecular glioblastoma,” in addition to radiologically showing a gliomatosis cerebri pattern of growth." (PMID 30419952, 2018). "Furthermore, several studies associate EGFR signaling with tumor progression of cancer, including breast, lung, head, and neck squamous cell carcinoma (HNSCC) and glioblastoma." (PMID 28611673, 2017). "EGFR is amplified in almost 50% of glioblastoma and 20% of anaplastic oligodendroglioma." (PMID 28415661, 2017). "All primary glioblastomas with EGFR amplification showed EGFR overexpression." (PMID 28785587, 2017). "For the common glioblastoma mutation EGFRvIII, the picture is a bit more clear, as currently approved EGFR-targeted treatments do not appear to be efficacious." (PMID 28513565, 2017). "PDK1 was the sole gene highly downregulated in both cells tested suggesting that targeting PDK1 and EGFR in mechanisms that bypass TMZ resistance may be a key factor in reverting the Warburg aerobic glycolysis metabolic pattern in glioblastoma." (PMID 28410193, 2017). "However, 70 to 90% of primary glioblastoma with EGFR overexpression demonstrated EGFR amplification." (PMID 28785587, 2017). "In glioblastomas, the high expression of both Rab7 and EGFR was shown in cell lines and xenografts." (PMID 28977851, 2017). "Blockage of EGFR/PI3K/Akt signaling axe could be an interesting therapeutic perspective to improve the survival of patients with glioblastoma." (PMID 28620312, 2017). "In addition to downregulating EGFR expression in glioblastoma cells, our data suggest that miR-135a affects EGFR turnover." (PMID 29268774, 2017). "In newly diagnosed glioblastoma patients, Rindopepimut—an epidermal growth factor receptor variant III (EGFR vIII)-specific peptide vaccine—reached phase III clinical testing but disappointingly, when combined with TMZ, failed to add significant OS benefit compared to TMZ alone." (PMID 29244745, 2017). "However, little effort has been spent on the development of suppressing EGFR expression with siRNA conjugates for glioblastoma therapy." (PMID 28181832, 2017). "They immobilized anti-EGFR RNA aptamers on the surface of modified glass and observed that these surface-immobilized EGFR aptamers could specifically capture glioblastoma cells with high specificity and sensitivity." (PMID 29036890, 2017). "Again, it has been recently reported that, in PDGFR signaling (in Reactome), transcriptional de-repression of PDGFR-β contributed to compensating for the effects of EGFR-TKIs in EGFR-mutant glioblastoma via an mTORC1- and extracellular signal regulated kinase-dependent mechanism." (PMID 28288164, 2017). "In our study, 26.15% (17/65) of glioblastoma patients showed EGFR amplification." (PMID 28785587, 2017). "Among 500 glioblastoma samples in TCGA, 173 samples were categorized as EGFR-amplified samples (red circle), and 246 samples (green circle) with normal or low DNA copy numbers and EGFR expression were categorized as EGFR-normal samples." (PMID 28830458, 2017). "Next, we studied whether PTUPB affects EGFR, a critical receptor tyrosine kinase that promotes glioblastoma angiogenesis and increases glioblastoma cell proliferation, migration and invasion." (PMID 29152086, 2017). "Due to most glioblastoma simultaneously express EGFR and HER2, bispecific antibody targeting EGFR and HER2 may be an effective strategy for the treatment of glioblastoma." (PMID 29209558, 2017).
glioblastoma (continued). "Unlike TKIs, the immunotoxins rE/CUS, like D2C7-(scdsFv)-PE38KDEL which can be activated in glioblastoma patients expressing wild-type EGFR only or co-expressing wild-type EGFR and EGFRvIII, is solely depends on the expression of EGFR rather than tyrosine kinase signaling cascade triggered by EGFR." (PMID 28445134, 2017). "Extensive cellular and molecular heterogeneity is a common feature of glioblastomas, including multiple alterations in the epidermal growth factor receptor (EGFR) gene that may affect treatment response." (PMID 28405930, 2017). "EGFR is involved with important cellular functions including cell growth, differentiation, survival, and migration, and deregulation of its signaling cascade is a driving force of glioblastoma tumorigenesis." (PMID 29189740, 2017). "Moreover, the expression of epidermal growth factor receptor (EGFR) in human glioblastoma cell lines was suppressed by miR-146b, which reduced their migration and invasion in vitro." (PMID 28294980, 2017). "The disappointing exploration of EGFR as a target in glioblastoma includes well-documented intra-tumoral heterogeneity of EGFR and amplification of other RTKs that could bypass EGFR inhibition." (PMID 29371993, 2017). "In glioblastoma, ZEB1 labeling index is higher in tumors with EGFR amplification or IDH1 mutation." (PMID 28945795, 2017). "Moreover, transduction of the YTS NK cell line (containing an EGFR-specific chimeric antigen receptor) with CXCR4 has been shown to enhance infiltration in glioblastoma xenograft models overexpressing CXCL12, resulting in improved survival." (PMID 28923105, 2017). "Therefore, melanoma and EGFR-modified glioblastoma cell lines provide diverse contexts to test the BCL2-profiling capacity of the designed proteins." (PMID 27805565, 2016). "Taken together, CH12 was combined with rapamycin, leading to a synergistic tumor-suppression effect on EGFRvIII+PTEN− glioblastoma in vivo via attenuating EGFR and the PI3K/AKT/mTOR pathway more effectively and reversing STAT5 activation caused by rapamycin treatment." (PMID 27029073, 2016). "EGFR amplification has been observed in 30–50% of glioblastomas, which is the highest grade glioma." (PMID 27713156, 2016). "Furthermore, it has been suggested that the interaction of EGFR with PDK in the mitochondrial matrix plays an important role in EGFR-induced tumor growth in glioblastoma multiforme." (PMID 27494858, 2016). "EGFR amplification was detectable in only 3.7% (4/107) of young adult glioblastomas." (PMID 26452024, 2016). "Interestingly, the EGFR gene is the most frequently amplified gene in glioblastoma, and it is a strong prognostic indicator in glioma." (PMID 27437777, 2016). "No studies have been published on the complete genetic variance of EGFR and glioblastoma prognosis." (PMID 27437777, 2016). "A series of recent reports demonstrated that constitutive activation of STAT3 in glioblastoma, as well as concomitant activation of various upstream signals involving epidermal growth factor receptor, specific methyltransferase, or PI3 kinase, is regarded as an important regulator of GSC stemness." (PMID 27145367, 2016). "Likewise, there were frequent CNGs of EGFR in a TCGA glioblastoma multiforme cohort (~45%), and of ERBB2 in nearly 14% of cases from a TCGA stomach cancer cohort." (PMID 27029057, 2016). "In addition to EGFR overexpression, loss of the tumour suppressor PTEN is a common feature in glioblastoma." (PMID 25502460, 2016). "Regarding glioblastoma, EGFRvIII, an oncogenic mutant of EGFR, is commonly found in glioblastoma." (PMID 26857455, 2016). "Notably, with the exception of three BRAF mutated glioblastomas concurrently harboring TERTp mutation, BRAF, H3F3A, IDH1, TERTp mutations and EGFR amplification were mutually exclusive." (PMID 26452024, 2016). "EGFR is known to play a role in TPA-induced glioblastoma cell proliferation." (PMID 27654969, 2016).
glioblastoma (continued). "Moreover, amplification of the epidermal growth factor receptor locus contributes to an acquired resistance to epidermal growth factor receptor inhibitors in glioblastoma cells." (PMID 27577169, 2016). "Expression of EGFR is well documented in ~60% of glioblastomas in both humans and dogs." (PMID 27050167, 2016). "Evidence indicates that the amplification of genes in DM may result in a dynamic regulation of gene expression and resistance to EGFR TKIs for EGFRvIII‐positive glioblastomas." (PMID 26422389, 2016). "It has been reported that berberine could suppress the constitutive activation of EGFR in human colon tumor, prostate cancer and glioblastoma." (PMID 27738318, 2016). "EGFR is driver of a number of cancers, and is overexpressed in ~54% of glioblastomas." (PMID 27218650, 2016). "Downregulated miR-21 inhibits the growth of human glioblastoma cells through EGFR pathway." (PMID 26690371, 2015). "EGFR variant III (EGFRvIII) is the most common mutation of the EGFR gene in glioblastoma, is present in 25–30 % of GB patients, and is absent in normal tissue." (PMID 26646075, 2015). "Fifty to sixty percent of primary glioblastoma tumors exhibit increased EGFR signaling." (PMID 25909451, 2015). "Blockage of miR-21 augments the efficacy of anti-EGFR therapy against glioblastoma." (PMID 26311740, 2015). "The GB138 glioblastoma model is characterized by EGFR gene copy number gain (EGFR amplification)." (PMID 26423602, 2015). "The tumoricidal and TMZ-sensitizing effects of BI2536 were uniformly observed across Ink4a/Arf(−/−) EGFRvIII glioblastoma clones that acquired independent resistance mechanisms to EGFR inhibitors, suggesting these resistant clones retain oncogenic stress that required PLK1 compensation." (PMID 26059434, 2015). "In glioblastomas, the growing list of candidate TAAs include the epidermal growth factor receptor (EGFR), tenascin-C (TNC), fatty acid binding protein 5 (FABP5), melanoma-associated antigen 3 (MAGEA3), glioma-expressed antigen 2 (GLEA2), and PHD finger protein 3 (PHF3)." (PMID 25944688, 2015). "Amplification of the EGFR locus is found in approximately 40 % of primary glioblastomas." (PMID 26502731, 2015). "Interestingly, among those genes we find the well-known glioblastoma oncogene EGFR and tumor suppressors CDKN2A and PTEN, but also novel candidates such as KRIT1 and PAOX described in the previous paragraph." (PMID 25679508, 2015). "Acknowledging that histopathological distinction of GBM-O from small cell glioblastoma can be difficult, it is likely that the latter variant was overrepresented in some studies taking glioblastomas as a starting point, particularly given their reportedly high frequencies of EGFR gene amplification." (PMID 25943885, 2015). "We determined whether glioblastoma cells with acquired resistance to EGFR inhibitors maintain cell states with oncogenic stress that require PLK1 as a compensatory mechanism." (PMID 26059434, 2015). "For example, using TCGA glioblastoma samples, Mueller and colleagues, have recently shown that the use of LCM is a necessary step to accurately correlate protein expression/activation with genomic alterations (e.g. PTEN loss or EGFR mutation)." (PMID 26468985, 2015). "A previous study of EGFRvIII in glioblastoma showed that Alu elements may be involved in intragenic rearrangement of EGFR to express EGFRvIII." (PMID 25658924, 2015). "In fact, it has been reported that EGFR-mutant glioblastomas may evade EGFR TKI by transcriptionally de-repressing PDGFRβ." (PMID 25380967, 2014).
glioblastoma (continued). "Additionally, we validated this observation by EGFR immunohistochemistry (IHC) using a tissue microarray (TMA) consisting of 19 independent glioblastoma specimens (5 G-CIMP+ and 14 G-CIMP-, p=0.0014)." (PMID 25277177, 2014). "Using this platform, we showed the EGFR signaling was suppressed in G-CIMP+ glioblastomas." (PMID 25277177, 2014). "In glioblastoma, EGFR gene amplification leads to receptor overexpression and rise of mutant forms." (PMID 24709958, 2014). "Importantly, a recent study validated Dyrk1A as a new target in EGFR–dependent glioblastoma: inhibition of Dyrk1A promoted degradation of EGFR and sharply decreased tumor cell growth and viability." (PMID 24676346, 2014). "In the present study, we found that nearly all Classical samples, including glioblastomas and anaplastic gliomas, harbored EGFR amplifications; also, Classical anaplastic gliomas had similar clinical outcomes to their glioblastoma counterparts and therefore should be treated more aggressively." (PMID 24755548, 2014). "Another puzzle in glioblastoma therapeutic development involved the observation that while Epidermal Growth Factor Receptor (EGFR) dysregulation is critically important in the pathogenesis of glioblastomas, EGFR inhibitors are clinically ineffective." (PMID 24657925, 2014). "Both full-length LRIG2 and LRIG2 ectodomain potently promote the proliferation and inhibited the apoptosis of glioblastoma cells in vitro and in vivo through physically interacting with EGFR, stabilizing EGFR, and enhancing EGFR activation and its downstream PI3 K/Akt pathway." (PMID 25353163, 2014). "Classical glioblastomas are reportedly characterized by EGFR amplifications." (PMID 24755548, 2014). "To test this hypothesis, we treated isogenic pairs of murine Ink4a-Arf−/− EGFRvIII glioblastoma lines expressing either IDH1-R132H or wild type IDH1 with the EGFR inhibitor, Gefitinib." (PMID 25277177, 2014). "The fact that TLX was identified as one of the significant mRNA responders to EGFR network perturbation when analyzed for a prognostic outcome prediction in glioblastoma multiforme, along with our results, highlight TLX as a crucial candidate for directed cancer therapy." (PMID 25356871, 2014). "To further verify that the results of our comparative gene signature analysis reflect genuine biology, we tested whether G-CIMP+ and G-CIMP- glioblastoma specimens harbor differing levels of pERK, a biomarker of EGFR pathway activation." (PMID 25277177, 2014). "Consistent with the EGFR amplification observed in EGFRvIII-bearing glioblastomas, EGFR was highly expressed in classical neurospheres derived from these tumors, but barely detectable in mesenchymal or preneural neurospheres that harbor EGFR wild-type gene." (PMID 24709958, 2014). "LRIG2 is permissive for oligodendroglial and glioblastoma-like brain tumour formation in a mouse model and downregulation of LRIG2 in cultured glioma cells led to ligand-mediated loss of the epidermal growth factor receptor (an RTK), cell cycle arrest and increased apoptosis." (PMID 24691552, 2014). "Epidermal growth factor receptor (EGFR) is amplified in 40% of human glioblastomas." (PMID 24650032, 2014). "Supporting this hypothesis, we found that G-CIMP+ Ink4a-Arf−/− EGFRvIII glioblastomas were more resistant to EGFR inhibition than their isogenic G-CIMP- counterparts." (PMID 25277177, 2014). "Additionally, here we demonstrate that promoter methylation patterns in G-CIMP+ glioblastoma facilitated deposition of repressive histone markers in the promoter region of EGFR and H-Ras, thereby suppressing expression of these genes." (PMID 25277177, 2014). "Decreased EGFR signaling in the G-CIMP+ glioblastomas suggest that these pathways may be peripheral in sustaining tumor growth and viability." (PMID 25277177, 2014). "The down-regulation of EGFR signaling suggests that G-CIMP+ glioblastomas may be less dependent on this mitogenic signaling pathway." (PMID 25277177, 2014).
glioblastoma (continued). "Finally, the G-CIMP+ Ink4a-Arf−/− EGFRvIII glioblastoma line was more resistant to the EGFR inhibitor, Gefitinib, relative to its isogenic G-CIMP- counterpart." (PMID 25277177, 2014). "Variant III is a deletion in the 267 position of the EGFR extracellular domain, not expressed in normal glioma tissue but only in glioblastoma cells." (PMID 25331657, 2014). "The EGFR gene is the most frequently amplified proto-oncogene in primary glioblastomas." (PMID 23472076, 2013). "Notably, CD133+ glioblastoma cell-induced tumors expressed higher levels of EGFR, Ang2, MMP2 and MMP9 proteins compared with CD133− cell-induced tumors, suggesting that CD133+ cell-induced tumors have a higher degree of malignancy." (PMID 23251243, 2013). "The results showed prediction of gefitinib effectiveness was difficult in glioblastoma by [125I]PYK, which might be due to the complicated expression of EGFR status in glioblastoma." (PMID 27408849, 2013). "Also of interest, TGFb3 was recently described as a candidate gene for resistance of human glioblastoma multiforme cell lines to erlotinib, another tyrosine kinase inhibitor targeting EGFR." (PMID 23372733, 2013). "They noted that the miR-7 directly targets EGFR, thus decreasing its level in glioblastoma cells." (PMID 23776563, 2013). "In addition, we showed that glioblastoma patients with lower levels of miR-219-5p had increased EGFR protein levels as compared to those having higher levels of miR-219-5p." (PMID 23690991, 2013). "In conclusion, our results indicate that activation of wild-type EGFR promotes invasion and glioblastoma development independent of angiogenesis, whereas loss of its activity results in angiogenic tumor growth." (PMID 23429996, 2013). "Such a drug combination may be useful in combinatorial therapy in patients with glioblastomas with EGFR overexpression." (PMID 23724064, 2013). "Glioblastoma cell lines with different expression of EGFR were tested." (PMID 27408849, 2013). "Dasatinib has anti-tumor effects on EGFRvIII-expressing glioblastoma models, including inhibition of invasion and induction of apoptosis although its anti-proliferative effect has also been reported in U87 cells expressing wild-type EGFR." (PMID 23408876, 2013). "EGFR expression identifies tumor-initiating cells with different tumorigenic capacities in human glioblastoma multiforme; enforced EGFR expression in CSCs enhanced their tumorigenic potential, while ectopic EGFR expression increased the in vivo tumorigenic capacity of EGFR-negative CSC lines." (PMID 23620784, 2013). "The poor efficacy of single treatments may be explained by concurrent activation of multiple RTKs in glioblastoma, including EGFR, ERBB2, PDGFRA and MET." (PMID 23874926, 2013). "The regulation of EGFR by miRNAs is reported in several cancers including glioblastoma." (PMID 23690991, 2013). "KRAS mutations have been found in >95% of pancreatic ductal adenocarcinomas, while overexpression of Epidermal Growth Factor receptor (EGFR), which induces Ras signaling, was found in 80–90% human head and neck squamous cell carcinomas and 40% of glioblastomas." (PMID 22438909, 2012). "EGFR gene amplification was detected in eight glioblastomas." (PMID 22159595, 2012).